Y_RNA (Y RNA )
Gene: Miscellaneous RNA gene on chromosome 1 (180,519,016 to 180,519,119, reverse strand). Ensembl gene ENSG00000206905.
Homologues: Orthologues: chimpanzee Y_RNA (98% identical), pig Y_RNA (88% identical), dog Y_RNA (86% identical), guinea pig Y_RNA (73% identical). Paralogues in human: Y_RNA (91% identical), RNY3 (90% identical), Y_RNA (90% identical), Y_RNA (89% identical), Y_RNA (88% identical), RNY3P1 (88% identical), RNY3P16 (88% identical), Y_RNA (87% identical), Y_RNA (86% identical), RNY3P14 (85% identical), RNY3P9 (85% identical), Y_RNA (85% identical), and 97 more.